XKRY (XK related, Y-linked (pseudogene) )
Synonyms: XKRY1
Gene: Long non-coding RNA gene on chromosome Y (17,768,980 to 17,770,560, reverse strand). Ensembl gene ENSG00000290724.
Homologues: Paralogues in human: XKRYP7 (100% identical).